CTHRC1 (collagen triple helix repeat containing 1)
Diseases named in the same sentence as CTHRC1 in open-access papers (continued):
Sharing a sentence is not in itself a finding about the gene and the disease.
fibrosis (9 papers, 2017 to 2026). the formation of excess fibrous connective tissue in an organ or tissue in a reparative or reactive process. "Specifically, the Cthrc1-OVA model will allow us to test the combination of OT-1 T cells/OVA antibodies together with potential immune-boosters in the fibrosis model." (PMID 37311583, 2023). "Thus, these in vivo data demonstrated that knockdown of Cthrc1 preserved cardiac function and prevented cardiac fibrosis and adverse remodeling in mice following MI." (PMID 41362745, 2026). "It is worth exploring whether Cthrc1 regulates cardiac fibrosis and whether its mechanism is mediated by the mmu-Hecw2_0009-miR-346-3p-Cthrc1 axis." (PMID 36003513, 2022). "Therefore, Meox1/Cthrc1/p-Smad2/3 signaling pathway might be a promising therapeutic target for cardiac fibrosis and remodeling in MI patients." (PMID 41362745, 2026). "Moreover, the discovery of proliferating Cthrc1+ fibrotic fibroblasts in other datasets of fibrosis in the skin, colon, liver, and heart suggests that the therapeutic potential of selective targeting of proliferating fibroblasts may be broadly applicable to other fibrotic diseases." (PMID 40875468, 2025). "This cluster expressed collagen triple helix repeat containing protein 1 (CTHRC1), previously shown to be increased in the lungs of patients with fibrosis." (PMID 35118101, 2021).
gastrointestinal stromal tumor (9 papers, 2015 to 2023). "Further, CTHRC1 expression has been reported to correlate with increased blood vessel density in mouse pancreatic tumor xenografts and in human gastrointestinal stromal tumors." (PMID 32053263, 2020). "Meanwhile, the recombinant of CTHRC1 protein could elevate the capacities of invasion and migration of primary gastrointestinal stromal tumors." (PMID 33102569, 2020). "Additionally, it was reported that the overexpression of CTHRC1 can significantly promote tumor angiogenesis in pancreatic tumors and gastrointestinal stromal tumors." (PMID 31798347, 2019). "Furthermore, being a prognostic factor, CTHRC1 promotes the invasiveness of gastrointestinal stromal tumors by activating Wnt/PCP-Rho signaling." (PMID 26452130, 2015). "In contrast, the overexpression of CTHRC1 in HEK293T cell and gastrointestinal stromal tumor (GIST) cell significantly inhibited the canonical Wnt pathway but activated the noncanonical Wnt/PCP pathway." (PMID 32848510, 2020).
rheumatoid arthritis (9 papers, 2014 to 2023). A chronic, systemic autoimmune disorder characterized by inflammation in the synovial membranes and articular surfaces. "We previously demonstrated the role of CTHRC1 in the migration of fibroblasts in rheumatoid arthritis as well as a potential marker for rheumatoid arthritis disease activity." (PMID 37109608, 2023). "The role of CTHRC1 in promoting tumor angiogenesis can serve as a research marker for the pathogenesis of autoimmune diseases such as rheumatoid arthritis." (PMID 32848510, 2020). "Elevated CTHRC1 levels were detected in patients with inflammatory conditions, including rheumatoid arthritis, and CTHRC1 is considered a marker of tissue remodeling, inflammation, or wounding." (PMID 31185973, 2019). "In a model of rheumatoid arthritis induced by anti-collagen antibody injection, Cthrc1 protein was localized in activated synovial fibroblasts." (PMID 24945147, 2014). "Binary logistic regression results of CTHRC1 plasma levels for rheumatoid arthritis diagnosis." (PMID 31249576, 2019). "As it has been reported that CTHRC1 is involved in tissue remodeling in rheumatoid arthritis and injured arteries by promoting the migration of fibroblasts, we hypothesized that CTHRC1 might have some role in the proliferation and motility of HCC cells." (PMID 24841500, 2014). "Since CTHRC1 participates in tissue remodeling in rheumatoid arthritis and injured arteries, we speculated that CTHRC1 may have a similar function in promoting NSCLC cell proliferation." (PMID 25238260, 2014). "This CTHRC1+ fibroblast was observed in AL, PJI, periodontitis, and synovium of osteoarthritis and rheumatoid arthritis." (PMID 36927352, 2023). "The preferential occurrence of CTHRC1+ fibroblast in inflammatory bone-related diseases (AL, PJI, osteoarthritis, rheumatoid arthritis, and periodontitis) and its presence in the AL and PJI samples lead us to hypothesize its role in bone-implant osseointegration." (PMID 36927352, 2023).
lymph node metastasis (8 papers, 2014 to 2024). "CTHRC1 expression associates with tumor stage, histology, lymph node metastasis, and poor clinical prognosis in KIRP." (PMID 33628726, 2020). "Notably, CTHRC1 expression was associated with tumor histology, stage, lymph node metastasis in KIRP." (PMID 33628726, 2020). "Moreover, CTHRC1 expression has associations with tumor histology, stage, lymph node metastasis in KIRP." (PMID 33628726, 2020). "Notably, higher expression of CTHRC1 was significantly associated with advanced T stage (P = 0.043, chi square test), lymph node metastasis (P = 0.023, chi square test) and TNM stage (P = 0.024, chi square test)." (PMID 28645305, 2017). "Age, menopause, clinical stage, tumor grade, tumor type, tumor size, lymph node metastasis and CTHRC1 level were correlated with the overall survival (p = 0.039, 0.011, < 0.001, 0.001, 0.025, 0.014, < 0.001 and 0.004, respectively)." (PMID 26452130, 2015). "Clinicopathologic analysis showed that CTHRC1 expression was significantly correlated with differentiation degree (p<0.001), clinical stage (p<0.001), T classification (p<0.001), lymph node metastasis (p=0.013) and distant metastasis (p<0.001)." (PMID 25238260, 2014). "Meanwhile, the high CTHRC1 level was related to lymph node metastasis, high grade, and stage." (PMID 33628726, 2020). "Meanwhile, the high CTHRC1 level in KIRC was related to lymph node metastasis high grade and stage." (PMID 33628726, 2020). "CTHRC1 expression was positively correlated with tumor size (p = 0.008), menopause (p = 0.037), clinical stage (p = 0.002) and lymph node metastasis (p < 0.001) and was also an important prognostic factor for the overall survival of EOC patients, as revealed by Kaplan-Meier analysis." (PMID 26452130, 2015). "Furthermore, high CTHRC1 expression was strongly correlated with the clinical stages, lymph node metastasis and distant metastasis." (PMID 25238260, 2014). "However, CTHRC1 expression was not independently associated with overall survival by multivariate Cox regression analysis in this cohort after adjustment for age, histology grade, lymph node metastasis and TNM stage." (PMID 28645305, 2017). "There was dramatical correlation between the CTHRC1 expression and FIGO clinical stage, lymph node metastasis, distance metastasis and ascites-derived cancer cells." (PMID 29021002, 2017). "By analyzing the expression characteristics of CTHRC1 in the clinical EOC samples, we found that CTHRC1 levels in EOCs with lymph node metastasis were remarkably higher than those in EOCs without lymph node metastasis." (PMID 26452130, 2015). "Furthermore, CTHRC1's effect on promoting the aggressiveness of NSCLC cells was verified by IHC results on the significant correlations between CTHRC1 expression and lymph node metastasis or distant metastasis in NSCLC patients." (PMID 25238260, 2014).
Arthritis (7 papers, 2012 to 2024). Inflammation of a joint. "Nevertheless, the similarities in CTHRC1 expression and function in rodent models of arthritis and RA patients are intriguing and provide a basis for future studies exploring the therapeutic and diagnostic potential of CTHRC1." (PMID 33670905, 2021). "We initially identified CTHRC1 through the genetic association of CTHRC1 gene polymorphisms with attenuation of proteoglycan-induced and collagen antibody-induced murine arthritis." (PMID 31249576, 2019). "Overall, these finding underscore the potential relevance of CTHRC1 as a marker in arthritis pathogenesis and also support our earlier findings showing positive association of CTHRC1 with IL-1β and IL-6 in a mouse model of arthritis." (PMID 31249576, 2019). "While CTHRC1 overexpression in fibroblasts confers pathologic effects in RA, there is also evidence for anti-inflammatory effects in a collagen antibody-induced arthritis murine model, suggesting that CTHRC1 can also play a protective role." (PMID 38891078, 2024). "Single-cell analysis of fibroblast lineages showed that LRRC15+ cells were enriched in arthritis, skin wound, fibrosis, and small and large pancreatic ductal adenocarcinoma, and these cells also showed high expression of CTHRC1." (PMID 37311583, 2023). "Cthrc1 is located within the proteoglycan induced arthritis 8 (Pgia8) locus of mouse chromosome 15, which controls PGIA severity in a sex-specific manner." (PMID 33670905, 2021). "We further showed that CTHRC1 expression in murine experimental arthritis is increased in the synovium and specifically detected in activated murine and human RA-FLS located at the synovial intimal lining and at the bone-pannus interface." (PMID 31249576, 2019). "CTHRC1 was established as a novel marker of activated synoviocytes in murine experimental arthritis and RA." (PMID 27430622, 2016). "We recently discovered that the synovial Cthrc1 mRNA directly correlates with arthritis severity in mice." (PMID 27430622, 2016). "In this study, we discovered that CTHRC1, otherwise a recognized marker of enhanced cancer metastases, is overexpressed in inflammatory conditions of murine arthritis." (PMID 27430622, 2016). "To corroborate the results based on murine arthritis, and to show evidence for a possible role of CTHRC1 in human RA, we collected clinical samples of blood plasma from healthy individuals and from patients with a diagnosis of RA." (PMID 27430622, 2016). "In both the murine arthritis model and in human arthritis, CTHRC1 protein was highly expressed compared to much lower expression in normal/basal conditions." (PMID 27430622, 2016). "CTHRC1 was found in activated fibroblast-like synoviocytes in the inflamed synovium in murine arthritis and in plasma from patients with RA." (PMID 27430622, 2016). "Immunohistochemical analysis of normal and inflamed synovium revealed highly inducible expression of CTHRC1 in arthritis (10.9-fold)." (PMID 27430622, 2016). "Cthrc1 RNA and protein levels were significantly increased in a mouse arthritis model." (PMID 38891078, 2024). "Interestingly, CTHRC1 protein serum levels were highest in a subgroup of SLE patients with arthritis." (PMID 33670905, 2021). "The linkage of CTHRC1 with arthritis development and disease severity in mice therefore raised the question of whether the corresponding human locus may be similarly linked to RA development in patients." (PMID 33670905, 2021). "Together, these findings corroborate observations in murine models of arthritis and indicate that CTHRC1 may have potential use as a biomarker for enhanced differential RA diagnosis." (PMID 33670905, 2021). "Interestingly, Cthrc1 null mice exhibited exacerbated arthritis with extensive inflammatory cell infiltration and pannus formation and significant bone erosion." (PMID 33670905, 2021).
Arthritis (continued). "However, of the over 200 genes located within this locus, Cthrc1 expression exhibited the strongest correlation with arthritis severity and levels of the pro-inflammatory cytokines IL-6 and IL-1β." (PMID 33670905, 2021). "CTHRC1 protein levels are increased in the plasma of RA patients but were either absent or detected only at very low levels in healthy individuals or patients suffering from other forms of arthritis, such as OA or reactive arthritis (ReA)." (PMID 33670905, 2021). "In mouse models of arthritis, CTHRC1 protein is detected at high levels at the site of joint or bone destruction and may be secreted from activated synoviocytes of the arthritic pannus." (PMID 31249576, 2019). "Due to clear inducibility in arthritis, specificity for the arthritic pannus, and the ability to be secreted into circulation, CTHRC1 could be a promising RA marker." (PMID 27430622, 2016). "Criteria were set as a 1.5-fold change threshold in the CAIA severity change and three genes were found including collagen triple-helix repeat-containing 1 (Cthrc1), C1q and TNF-related protein 3 (C1qtnf3), and ADAMTS-12, which were all associated with both gender and arthritis." (PMID 24876675, 2014). "Therefore, CTHRC1 may be instrumental as an easy-to-measure plasma marker that can improve RA diagnosis and discriminate RA from OA and potentially other forms of arthritis with an inflammatory component." (PMID 31249576, 2019). "At the current level of understanding, CTHRC1 may be instrumental as an easy-to-measure plasma marker that can significantly improve the diagnosis of RA and distinguish RA from OA and other forms of arthritis with an inflammatory component." (PMID 31249576, 2019). "In a collagen antibody-induced arthritis model, CTHRC1 was anti-inflammatory and inhibited osteoclast differentiation, as well as joint destruction indicating that CTHRC1 may be part of a protective repair mechanism activated in the inflamed synovium in response to joint and bone erosion." (PMID 31249576, 2019). "Thus, CTHRC1 appears to confer potent anti-inflammatory effects in the synovium and may play an important and broader role in the regulation of the immune response in this mouse model of arthritis." (PMID 33670905, 2021). "Thus, CTHRC1 may serve as a marker for the development of arthritis in SLE." (PMID 33670905, 2021). "In this study, the first pilot cohort of patients with RA had significantly increased circulating CTHRC1, and high CTHRC1 correlated with increased CRP and with aggravated arthritis." (PMID 27430622, 2016). "IHC staining of the naïve synovial joints of hind paws and knees was negative, while the amount of CTHRC1 was dramatically increased in arthritis." (PMID 27430622, 2016).
liver fibrosis (7 papers, 2018 to 2026). "In addition, Cthrc1 promotes cardiac fibrosis and carbon tetrachloride (CCl4)- and thioacetamide-induced hepatic fibrosis; however, the mechanism underlying Cthrc1 expression remains unclear." (PMID 36690273, 2023). "CTHRC1 has been demonstrated to interact with stellate cells in the liver (HSCs) and promote liver fibrosis." (PMID 37444482, 2023). "In summary, our results indicated that the well-developed actin cytoskeleton and Cthrc1 expression due to drebrin in myofibroblasts promoted cardiac and hepatic fibrosis, suggesting that drebrin is a therapeutic target molecule for fibrosis." (PMID 36690273, 2023). "Increased Cthrc1 expression has been previously detected in the fibrotic livers of CCl4- or thioacetamide-administered mice, and autocrine Cthrc1 has been found to activate HSCs and promote hepatic fibrosis." (PMID 36690273, 2023). "Previously, CTHRC1 was found to activate hepatic stellate cells (HSCs) and promote liver fibrosis." (PMID 37444482, 2023). "We confirmed that Cthrc1 expression increased during CCl4-induced hepatic fibrosis." (PMID 36690273, 2023). "CTHRC1 played an important role in attenuating fibrosis in hepatic fibrosis." (PMID 29988590, 2018). "An additional profibrogenic micro-environmental factor is the collagen triple helix repeat containing 1 (CTHRC1), which is secreted from HSC during liver fibrosis." (PMID 31718044, 2019).
osteoporosis (7 papers, 2008 to 2025). A condition of reduced bone mass, with decreased cortical thickness and a decrease in the number and size of the trabeculae of cancellous bone (but normal chemical composition), resulting in increased fracture incidence. "It is noteworthy in this article that Cthrc1 may have a potential role in treating osteoporosis, because we observed that osteoblast-specific overexpression of Cthrc1 in mice attenuates bone loss which is induced by OVX, an accepted preclinical disease model of postmenopausal osteoporosis." (PMID 18779865, 2008). "In fact, a recent report showed that USC-EVs prevent osteoporosis by enhancing bone formation through the shuttling of collagen triple-helix repeat containing 1 (CTHRC1) to OBs and by reducing osteoclastic bone resorption via osteoprotegerin (OPG)." (PMID 34206294, 2021). "Our results suggest that autologous USC-EVs represent a promising novel therapeutic agent for osteoporosis by promoting osteogenesis and inhibiting osteoclastogenesis by transferring CTHRC1 and OPG." (PMID 31263627, 2019). "Our results indicate that Cthrc1 increases bone mass as a positive regulator of osteoblastic bone formation and offers an anabolic approach for the treatment of osteoporosis." (PMID 18779865, 2008). "Hence, Cthrc1 constitutes a potential target of an anabolic therapy for osteoporosis and the therapeutic effects are expected to be enhanced with antiresorptive drugs." (PMID 18779865, 2008). "The function of Cthrc1 as a stimulator of bone formation without affecting bone resorption is very promising, because most types of drugs which are currently used for the treatment of osteoporosis are antiresorptive in nature and insufficient for restoring bone volume in osteoporotic patients." (PMID 18779865, 2008).
keloid (6 papers, 2014 to 2026). An irregularly shaped, elevated mark on the skin caused by deposits of excessive amounts of collagen during wound healing. "For example, in smooth muscle cells and keloid fibroblasts, Cthrc1 has been reported to reduce collagen deposition by suppressing TGF-β/Smad pathway 52-54." (PMID 41362745, 2026). "Investigations utilizing Cthrc1−/− mouse models and treatment with exogenous Cthrc1 indicated a protective role of Cthrc1 in keloids." (PMID 38891078, 2024). "In contrast, single-cell RNA sequencing studies of human keloid tissue samples revealed the crucial involvement of local macrophages in the expansion and differentiation of CTHRC1-positive fibroblasts." (PMID 38891078, 2024). "To further assess the means for this regulation of CTHRC1 expression in the skin, we examined chromosomal accessibilities of the CTHRC1 promoter region with use of ATAC-seq datasets involving keloids and lungs in FibROAD." (PMID 35277958, 2022). "When searching for the expression profile of CTHRC1 in other tissues with fibrosis, we found similar effects within the skin, with CTHRC1 being elevated in both keloid and wound healing fibroblasts." (PMID 35277958, 2022). "TGF-β regulates the expression of CTHRC1 in a concentration-dependent manner in keloids, and excess CTHRC1 reverses collagen synthesis." (PMID 32848510, 2020). "The precedence for this stems from the examination of TGF-β and CTHRC1 expression in keloids." (PMID 38891078, 2024). "Similarly, enhanced Cthrc1 expression or treatment of keloid fibroblasts with recombinant Cthrc1 decreased collagen I synthesis in both normal skin fibroblasts and keloid fibroblasts in vitro by inhibiting TGF-β/Smad pathway activation." (PMID 38891078, 2024). "Although CTHRC1 inhibits TGF-β signaling, which induces phosphorylation of Smad2/3 in smooth muscle cells and collagen type I expression in keloid fibroblasts, we could not confirm such an inhibitory effect in SW480-CTHRC1 cells (data not shown)." (PMID 24504172, 2014).
colon adenocarcinoma (5 papers, 2012 to 2024). "In Western blot analysis of CTHRC1, a monoclonal antibody designated CH21D7 was able to detect a band of the apparent molecular weight of a full-length CTHRC1 in the human colon adenocarcinoma cell line HT29." (PMID 22321245, 2012).